S100A9 (S100 calcium binding protein A9)
Diseases named in the same sentence as S100A9 in open-access papers (continued):
Sharing a sentence is not in itself a finding about the gene and the disease.
tumor (continued). "The detection in the blood of S100A8/S100A9 released by neutrophils in the tumour microenvironment suggests they could be utilised as a serum biomarker for diagnosis or prognosis of CA." (PMID 35842572, 2022). "Consistent with previous studies, the expression of S100A9 in tumor cells was significantly increased after M2 macrophages were co-cultured, and the expression of TNFRSF11B was significantly reduced, which may increase the malignancy of tumor cells." (PMID 35397536, 2022). "To test this hypothesis, we first investigated the expression of S100a9 and its partner, S100a8, in different cell subpopulations in the mammary gland, different developmental stages, and in tumor tissues." (PMID 35304461, 2022). "Both approaches and further analysis demonstrate that BRCA1 negatively regulates S100A9 in mammary epithelium and the activated S100A9-CXCL12 signaling upon BRCA1 deficiency acts as a driving signaling to establish the tumor microenvironment, which renders tumor cells insensitive to ICB." (PMID 35304461, 2022). "Notably, knockdown of BAP18 by short hairpin RNA in TNBC cells suppressed xenograft tumor growth in mice, the noted effect was partially reverted by re-expression of S100A9 in BAP18-depleted cells." (PMID 35484101, 2022). "Targeting S100A8 and S100A9 may help stop tumor cells from migrating to places where they can spread." (PMID 35783639, 2022). "Moreover, FGL1 was positively associated with the CD3D expression and negatively associated with FOXP3, S100A9, and TPSB2 within the tumor site." (PMID 36268014, 2022). "In contrast, overexpression of S100A9 remarkably enhanced tumor growth." (PMID 36041055, 2022). "Notably, inhibition of S100A9 by in vivo‐optimized RNAi or Tas administration significantly attenuated HCC‐PDX tumor growth." (PMID 36041055, 2022). "To address whether BAP18 promotes TNBC tumor growth through regulating S100A9, we re-expressed Flag-S100A9 in LM2-4175 cells stably expression shBAP18, and then 1 × 106 cells were injected into the mammary fat pad of 6-week-old female BALB/c athymic nude mice." (PMID 35484101, 2022). "Similarly, higher S100A9 expression was correlated with higher T stage, tumor stage, and tumor grade and worse OS in the TCGA‐LIHC database." (PMID 36041055, 2022). "Co-staining for CK18 and S100a9 in the mammary epithelium at multiple developmental stages, tumor-adjacent and tumor tissues also revealed increased S100a9 protein levels, indicating that loss of Brca1 stimulates S100a9 expression at both the mRNA and protein levels in mammary tissues." (PMID 35304461, 2022). "In summary, our study illustrated that preoperative TACE may increase the expression of S100A9 by creating a hypoxic tumor microenvironment, leading to the formation of metastases and resulting in a high rate of tumor recurrence in HCC patients." (PMID 36041055, 2022). "The expression of both Calprotectin subunits S100A8 and S100A9 was examined in clinical PeCa specimens using three TMAs reflecting the tumor center (TMA TC, n = 63), the invasion front (TMA IF, n = 57), and the corresponding lymph node metastases (TMA LM, n = 22)." (PMID 36303837, 2022). "Indeed, tumor cell proliferation in S100A9 genetically deficient mice was unaffected in an Mdr2−/− inflammation-driven HCC mouse model, whereas tumor cell proliferation was decreased in a DEN-induced HCC model developing in the absence of chronic inflammation." (PMID 36232334, 2022). "Furthermore, ectopic expression of PGAM5 rescued the effects of S100A9 knockout and promoted tumor metastasis in vivo." (PMID 36041055, 2022). "Moreover, re-expression of S100A9 in BAP18-depleted TNBC cells partially rescued reduced xenograft tumor growth in mice by BAP18 knockdown." (PMID 35484101, 2022). "Moreover, through the in depth analysis of large publicly available databases, we show that TNBC, unlike Luminal-A and Luminal-B BC subtypes, harbors higher levels of both S100A8 and S100A9 respect to non-tumor breast tissues." (PMID 35655319, 2022).
tumor (continued). "Rescue of PGAM5 in S100A9‐knockout cells mostly restored tumor growth and migration in vitro and in vivo, suggesting a direct role of PGAM5 in promoting tumor progression that is responsible for S100A9‐mediated mitochondrial fission, ROS production, and EMT programs." (PMID 36041055, 2022). "S100A9 has been recognized as a targetable protein with high expression in multiple tumor types." (PMID 34519180, 2021). "S100A8 and S100A9 expression was found significantly higher in cancer tissues than in para-cancer tissues and correlated with tumor differentiation, which may be a potential marker for poor prognosis in NSCLC." (PMID 33567747, 2021). "Indeed, S100A8 and S100A9 expression was significantly reduced in the presence of anti-TGF-β antibodies in tumor-bearing mouse sera." (PMID 34201758, 2021). "In addition, peptibodies, peptide-Fc fusion proteins that target S100A8 and S100A9, reduce tumor burden in multiple cancer models." (PMID 33801279, 2021). "Conversely, low extracellular CLP concentrations finally promote migration of cancer cells and S100A8 and S100A9 expression knockdown and may increase malignancy and tumor invasion." (PMID 33567747, 2021). "Moreover, clinical analysis implied that high expression of S100A9 in tumor stroma predicted advanced stage, poor response rate and early recurrence." (PMID 34045609, 2021). "Indeed, the expression of proteins S100A8 and S100A9 is up-regulated in several tumor types (breast, prostate, colon, melanoma, etc.)." (PMID 33801279, 2021). "Moreover, high S100A9 expression in tumor tissue correlated with an unfavorable prognosis in HCC patients in subgroups divided by the median value and minimum P-value approach." (PMID 34157683, 2021). "The results from the nude mouse xenograft model showed that co-injection with HCT116/Fn-treated Mφ significantly accelerated the tumor growth, and this effect was partially blocked by silencing S100A9 expression in Mφ in the nude mice co-injected with HCT116/(Fn + siS1A00A9)-treated Mφ." (PMID 34093546, 2021). "Moreover, S100A8 and S100A9 neutralizing antibodies have been shown to block the recruitment of both myeloid cells and circulating tumor cells." (PMID 33801279, 2021). "For example, tasquinimod, a second-generation oral quinoline-3-carboxamide that has been shown to bind S100A9 in the tumor microenvironment, blocks engagement of S100A9 with RAGE, and thus, prevents activation of downstream signaling pathways that lead to production of pro-inflammatory cytokines." (PMID 34975408, 2021). "Upregulation of S100A8 and S100A9 occurs in various human cancer types and may participate in tumor growth, metastasis, angiogenesis and immune evasion." (PMID 34485305, 2021). "The improved efficacy of the S100A9‐targeted formulations can be attributed to successful tissue targeting of the lung resulting in the immunomodulation of the lung tissue microenvironment favorable for metastatic tumor cell rejection." (PMID 34519180, 2021). "Studies have revealed that S100A9 induced activation of NF-kB which participate in a broad range of intracellular and extracellular functions by regulating angiogenesis, tumor migration, wound healing, cell apoptosis, proliferation, differentiation, and inflammation." (PMID 34689294, 2021). "S100A9 might also interact with Toll-like receptor 4 (TLR4) expressed on tumor cells where it promotes tumor growth." (PMID 34572138, 2021). "Moreover, S100A8 and S100A9 proteins contribute to tumor growth, metastasis development, angiogenesis, and immune escape in a wide variety of solid cancers." (PMID 33801279, 2021). "S100A9 has both tumor supportive and tumor suppressive roles." (PMID 34765739, 2021). "In addition, it has become increasingly evident that S100A9 acts as a potent amplifier of inflammation in tumor." (PMID 34689294, 2021).
tumor (continued). "Previous studies have shown that S100A9 acts as a chemotactic molecule to recruit inflammatory cells or immunocytes, such as MDSCs and neutrophils, to the tumor microenvironment, resulting in a proinflammatory microenvironment that promotes tumor progression." (PMID 34157683, 2021). "We can hypothesize that S100A8 plays a prominent regulatory role in tumor biology in comparison with S100A9, yet a larger study could identify more relationships and differences in S100A9 as well." (PMID 33466593, 2021). "S100A9 could recruit myeloid-derived suppressive cells (MDSC) in tumor microenvironment through interaction with RAGE or TLR on MDSC16." (PMID 34045609, 2021). "Indeed, inhibition of S100A9 using quinoline-3-carboxamide derivatives such as tasquinimod has shown anti-tumor effects in several pre-clinical models, through modulation of the tumor microenvironment." (PMID 33801279, 2021). "Furthermore, immunofluorescence double staining revealed that the primary S100A9-expressing cells in adjacent nontumoral tissue were CD15+ neutrophils, and both CD68+ macrophages and CD15+ neutrophils expressed S100A9 in HCC tumor tissues." (PMID 34157683, 2021). "Except for S100A9, other genes were down-regulated in tumor tissues." (PMID 34490047, 2021). "Elevated MDSCs and S100A9 were indicated in peripheral blood and tumor tissue from CRC patients." (PMID 33117687, 2020). "Additionally, tumor cells were able to secrete S100A9 protein to extracellular stroma, stimulate accumulation of inflammatory cells and offer a pre-metastatic niche in the tumor microenvironment." (PMID 33203795, 2020). "In an 80 μm resolution MALDI MS image series of the 4–17 kDa range of LMW proteins, S100A8 and S100A9 were essentially undetectable in the healthy stromal areas of the specimen, while they were present in the tumor and tumor stroma as well as in the healthy epithelial region." (PMID 32733643, 2020). "Finally, as knockdown of S100A8 and S100A9 revealed the most prominent effect on clonogenic growth and cell migration, we tested the in vivo relevance of our findings in tumor xenograft assays." (PMID 32503348, 2020). "Moreover, in an in vitro experiment, MDSC isolated from the PALNs of ME180-GCSF cell-derived tumor-bearing mice expressed high levels of S100a8 and S100a9 mRNA." (PMID 32170086, 2020). "It is notable that S100A9 may serve as a tumor biomarker in serum, urine, and digestive fluid for early molecular diagnosis." (PMID 33203795, 2020). "Overexpression of S100A9 heightened tumorigenesis, tumor progression and recurrence." (PMID 33203795, 2020). "Previous researches have proposed that S100A9 participated in Ras-mediated tumor progression." (PMID 33203795, 2020). "In addition, exogenous IL-33 enhanced the immunostaining intensity and mRNA levels of S100A9, which induced epithelial-mesenchymal transition and led to tumour occurrence." (PMID 33308251, 2020). "In addition, increased percentages of CD33+S100a9+ cells in BTC tumour tissue correlated with higher tumour grade, the presence of satellite lesions, and more poorly differentiated tumours." (PMID 32747748, 2020). "S100A9 expression in tumor and adjacent normal tissues from CRC patients was detected by IHC." (PMID 31620141, 2019). "Additionally, increased S100A9 expression in CRC was detected in five randomly selected CRC patients' tumor tissues and adjacent normal tissues by Western blot." (PMID 31620141, 2019). "S100A9 expression is significantly higher in a variety of tumours compared to normal tissues or healthy individuals, and may be a potential marker for poor prognosis of cancer patients." (PMID 30918751, 2019). "S100A9 secreted from tumor cells is an important regulator of tumor microenvironment." (PMID 31727865, 2019). "S100A8 and S100A9 are known to have a dual role in tumor progression." (PMID 30808902, 2019).
tumor (continued). "As we establish, higher expression of S100A8 and S100A9 is indicative of the presence of pro-tumorigenic microenvironment and also predict prognosis, their expression levels in the post-operative tumor have the possibility to serve as a biomarker for predicting survival." (PMID 30808902, 2019). "Elevated S100A9 and MDSCs were found in tumor tissue and peripheral blood from CRC patients." (PMID 31620141, 2019). "S100A9 mRNA expression levels were significantly higher in tumor than in normal bone tissues." (PMID 31055998, 2019). "S100A9 have gained interest because it functions as a chemokine for regulating inflammatory cell or immunocyte, which creates a proinflammatory microenvironment to facilitate tumor growth and metastasis." (PMID 31620141, 2019). "Furthermore, our results indicate the essential role of S100A9 in tumor-environment interactions in bone marrow and greatly improve our understanding of the role of the NLRP3 inflammasome in cellular senescence." (PMID 31727865, 2019). "Additionally, exosomes shed by tumoral MDSCs from CRC patients enhanced the stemness of CRC cells through S100A9 and sequential tumor progression." (PMID 31559140, 2019). "In our study, MDSCs isolated from the tumors of Py-treated mice showed significant reduction in the expression of phosphorylated STAT proteins, S100A9, and Survivin at both the mRNA and protein levels, further explaining their reduced proportion in the tumor tissues." (PMID 30979375, 2019). "However, S100A9 serum levels had relevance to the tumor metastasis status, and TNC levels were increased in relapsed patients." (PMID 31632476, 2019). "On the other hand, a wide range of pro-inflammatory factors, e.g., PGE2, TNF, IL-1β, IL-6, S100A8, S100A9, IFNγ, IL-4, IL-10, and IL-13 secreted by cancer cells and leukocytes residing in the tumor inhibit the differentiation of myeloid progenitors and enhance their suppressive capacity." (PMID 30349530, 2018). "Tumor and control tissue levels of S100A9 protein were validated using immunoblotting method." (PMID 29568375, 2018). "We next analyzed the role of S100A9 in HBx-mediated tumor-promoting effect in HCC." (PMID 29795379, 2018). "Here, we reported that CCL5-deficiency dramatically inhibited S100a9 secretion in CD11bhiF4/80low TAMs, which contributed to the ability of CD11bhiF4/80low TAMsCCL5−/− in promoting the infiltration of CD8+ T cells into the central tumor area." (PMID 29991744, 2018). "Indeed inhibition of S100A9 by tasquinimod, a quinoiline-3-carboxamide derivative, through modulation of the tumour microenvironment has shown promising effects in preclinical models." (PMID 29955397, 2018). "Tumor cells induce production of S100A9 protein in the myeloid precursors, which prevents the differentiation of myeloid cells to macrophages and dendritic cells resulting in the development of myeloid-derived suppressor cells (MDSCs) in the tumor microenvironment." (PMID 29568375, 2018). "Among them, 13 proteins correlated with clinicopathological parameters and of these proteins, eight proteins were identified in neoplastic islands (ACTR2, CSTB, COL1A2, LTA4H, PGK1, NDRG1, S100A8, S100A9) and five proteins were identified in tumor stroma (COL6A1, FSCN1, ITGAV, MB, THBS2)." (PMID 30185791, 2018). "Accordingly, peptibodies against S100A9 led to reduced MDSC recruitment in tumor-bearing mice." (PMID 30349530, 2018). "Moreover, S100A9 can recuit MDSC in tumor sites, which suppresses T cell function and promote tumor metastasis." (PMID 27021626, 2016). "This indicated that S100A9 might mediate the tumor progression in OS cells by promoting cellular migration and invasion, which was linked to MAPK and NF-κB signaling pathways." (PMID 27020242, 2016). "Moreover, S100A9 can recruit myeloid derived suppressor cells (MDSC) in tumor sites and result in invasive phenotype of cancer." (PMID 27021626, 2016). "In our study, S100A9 independently promoted the tumor growth, migration and invasion in vitro." (PMID 27020242, 2016).
tumor (continued). "Tasquinimod, a novel oral quinoline-3-carboxamide derivative, was shown to have multiple effects on the tumour microenvironment including possible binding to S100A9 protein which leads to the inhibition of interaction between S100A9 and receptors such as RAGE and TLR4." (PMID 26880885, 2016). "High S100A9 expression in stroma but not in tumor cells was significantly associated with non-well differentiation and recurrence." (PMID 26315114, 2015). "The stimulatory action of tumor S100A9 was mainly on cell migration and invasion." (PMID 26315114, 2015). "However, in SCC12 cells, overexpressing S100A8 and/or S100A9 had increased proliferation and cell migration capacity in vitro and also showed increased tumor growth in vivo in SCID mice." (PMID 26053695, 2015). "In addition to increasing cell migration and invasion, ectopic S100A9 expression in tumor cells promoted xenograft tumorigenesis as well as the dominant expression of myeloid cell markers and pro-inflammatory IL-6." (PMID 26315114, 2015). "S100A9 was detected in the CD68+ macrophages of tumor stroma." (PMID 26315114, 2015). "Thus binding of tasquinimod to S100A9, and thereby inhibiting its interaction with receptors on myeloid cells, is a possible mechanism for an altered migration of myeloid cells into the tumor." (PMID 26673090, 2015). "In addition to the detection of S100A9 protein in tumor cells, S100A9 was also abundantly expressed in the tumor stroma." (PMID 26315114, 2015). "Furthermore, previous studies have shown that low concentration of S100A9 induces pro-tumor proliferative effects." (PMID 26431492, 2015). "Together, S100A9 deregulation in tumor stroma may serve as an early poor prognosis marker and have a role in tumor recurrence." (PMID 26315114, 2015). "More studies are needed to examine if tumor S100A9 can enhance HSC3-induced metastasis." (PMID 26315114, 2015). "In addition to its up-regulation in several epithelial tumors, S100A9 is also abundantly expressed in tumor infiltrating immune cells." (PMID 26315114, 2015). "Interestingly, S100A9 expression correlated with the histological Grade of tumor with a more dramatic downregulation observed in poorly differentiated tumors." (PMID 26788548, 2015). "Since S100A9 was originally identified in myeloid cells, confocal immunofluorescence microscopy was used to study the type(s) of myeloid cells expressing S100A9 in tumor stroma of clinical specimens." (PMID 26315114, 2015). "Higher levels of ARG1, iNOS, S100A8 and S100A9 in CD11b+Gr-1 + cells from Lewis- and B16- tumor bearing mice could be detected as compared to the counterparts from tumor-free mice." (PMID 26285119, 2015). "Endothelial-cells-derived inflammatory chemotaxins S100A8 and S100A9 induced by distant primary tumor may attract Mac1 (macrophage antigen 1) (+)-myeloid cells to the premetastatic site to promote tumor growth in the lung." (PMID 24587996, 2014). "Furthermore, S100A8 and S100A9 are expressed by HCC tumour cells as well as by other tumours of epithelial origin including lung, breast, gastric, and prostate." (PMID 24333183, 2014). "Furthermore, S100A9 also has a role in recruiting both inflammatory cells and tumour cells to metastatic sites." (PMID 24162378, 2014). "Both, FTL and S100A9 are increased in serum under inflammatory conditions, and they might thus represent tumour-related inflammatory responses." (PMID 25177240, 2014). "In addition, STAT3 up-regulates S100A9 in hematopoietic progenitor cells, which inhibits further differentiation to DCs and retains these cells as MDSCs, leading to tumor tolerance." (PMID 24339824, 2013). "Moreover, S100A9 in CD11b+CD14+ monocytic MDSC correlates with tumour response to platinum-based chemotherapy with low CD11b+CD14+S100A9+ having longer progression-free survival." (PMID 26464846, 2013).